KCNN4 (potassium calcium-activated channel subfamily N member 4)
Diseases named in the same sentence as KCNN4 in open-access papers (continued):
Sharing a sentence is not in itself a finding about the gene and the disease.
iron overload (2 papers, 2017 to 2021). "As DHSt due to a Gardos channel KCNN4 mutation is likely to be much more prevalent than reported, confirmation is critical to counsel patients and families appropriately, avoid unnecessary splenectomy and recognize iron overload early in the course of this disorder." (PMID 35844691, 2021).
ischemic cardiomyopathy (2 papers, 2013 to 2021). Ischemic cardiomyopathy is a cardiomyopathy in which a weakness in the muscle of the heart due to inadequate oxygen delivery to the myocardium with coronary artery disease being the most common cause. "Intramyocardial injection of EDCs after KCNN4-gene overexpression markedly increases the salutary effects of EDCs on cardiac function, viable myocardium and peri-infarct neovascularization in a well-established murine model of ischemic cardiomyopathy." (PMID 34400625, 2021).
aortic stenosis (1 paper, 2025). Aortic valve stenosis is a aortic valve disease caused by the incomplete opening of the aortic valve. "Data show that TGF-β1 induces KCa3.1 (intermediate conductance calcium-activated potassium channel protein 4, KCNN4) channel expression in aortic valve tissue fibroblasts in patients with aortic stenosis." (PMID 40142664, 2025).
Arthritis (1 paper, 2022). Inflammation of a joint. "Specifically, following intradermal injection of chicken collagen type II into the base of the tail of KCNN4-/- mice on days 0 and 21, no KCNN4-/- mice developed clinical evidence or histological signs of arthritis, in contrast to wild-type mice." (PMID 36275686, 2022).
colorectal adenocarcinoma (1 paper, 2025). The most common type of colorectal carcinoma. "To further explore the regulation of KCNN4 expression in cancer, we analyzed its association with common driver gene mutations in PAAD and colorectal adenocarcinoma (COAD)." (PMID 40952239, 2025).
cystic kidney disease (1 paper, 2025). A congenital or acquired kidney disorder characterized by the presence of renal cysts. "Renal Kcnn4 upregulation in all tested Pkd1 mouse models of ADPKD suggests that Kcnn4 plausibly contributes to renal cyst growth in ADPKD." (PMID 41122971, 2025). "Absence of microscopic renal anomalies and apparent fibrosis in Kcnn4–/– adult mouse kidneys confirmed utility of testing effects of Kcnn4 inactivation on renal cyst appearance and enlargement." (PMID 41122971, 2025). "In rapidly and/or slowly progressive mouse Pkd1 models, Kcnn4 inactivation slowed renal cyst growth; attenuated PKD-stimulated cAMP and ERK/Myc signaling pathways; reduced PKD-associated ciliary elongation, cell proliferation, and fibrosis; improved renal function; and prolonged survival." (PMID 41122971, 2025). "Upregulation of KCNN4 expression in human ADPKD kidneys, as well as in kidneys of several mechanistically distinct Pkd1 mutant mouse models, is consistent with a role of KCa3.1 in cystic kidney disease." (PMID 41122971, 2025).
depression (1 paper, 2022). "In addition, the expression levels of KCNN4, MOG, and SNHG12 genes can influence inflammatory factors, which may affect grip strength and depression by influencing the inflammatory response." (PMID 36520780, 2022).
emphysema (1 paper, 2020). "After Kcnn4 silencing lung edema in the Scnn1btg/+ mouse was reduced to levels similar to the control animals and concomitantly, we observed less damage associated with emphysema." (PMID 32814712, 2020). "Kcnn4 silencing in the Scnn1b-transgenic mouse (Scnn1btg/+), a model of muco-obstructive lung disease triggered by increased epithelial Na+ absorption, improved MCC, reduced Na+ absorption, and did not change the amount of mucus but did reduce mucus adhesion, neutrophil infiltration, and emphysema." (PMID 32814712, 2020).
hereditary anemia (1 paper, 2022). "A previous article reported the H340N KCNN4 mutation in a genetic study enrolling 155 patients with suspected hereditary anemia." (PMID 36003639, 2022).
hereditary hemolytic anemia (1 paper, 2020). "Gardos channelopathy (Gardos-HX) or type 2 stomatocytosis/xerocytosis is a hereditary hemolytic anemia due to mutations in the KCNN4 gene." (PMID 33519508, 2020).
intracranial aneurysms (1 paper, 2025). "Furthermore, RNA-sequencing data demonstrated elevated expression of KCNN4 and UGCG in ruptured intracranial aneurysms compared to unruptured ones." (PMID 40500739, 2025).
metastatic melanoma (1 paper, 2021). A melanoma that has spread from its primary site to another anatomic site. "In order to test whether the high expression and functionality of KCNMA1, KCNN4, and TRPM2 is specific to (primary) IGR39 cells, we analyzed several publicly available datasets on gene expression in melanocytes, as well as primary and metastatic melanoma cell lines." (PMID 34445066, 2021).
obstructive lung disease (1 paper, 2020). "The clearance of beads also showed increased values for speed and distances, indicating that Kcnn4 silencing improved MCC in the muco-obstructive lung disease model." (PMID 32814712, 2020).
osteonecrosis (1 paper, 2021). A none disease characterized by death of bone tissue due to a lack of blood supply. "Because the mechanism of bisphosphonates involves the suppression of Kcnn4, we postulated that the downregulation of this protein may also be important for the progression of bisphosphonate-induced osteonecrosis." (PMID 34279472, 2021). "The higher OPG and lower TRAP, RANKL, and Kcnn4 expression levels that were detected in the bones of IV-BP derived MRONJ patients can be correlated with enhanced suppression of osteoclast resorbing activity and subsequent osteonecrosis exacerbation." (PMID 34279472, 2021).
pemphigus (1 paper, 2023). Pemphigus is a group of rare autoimmune diseases that cause blistering of the skin and mucous membranes (mouth, nose, throat, eyes, and genitals).This conditioncan occur at any age, but often strikes people in middle or older age. "It has been reported that potassium calcium-activated channel subfamily N member 4 (KCNN4) channels are upregulated on the surface of B cells in patients with pemphigus treated with rituximab." (PMID 37464309, 2023).
primary immunodeficiency (1 paper, 2022). "Moreover, Kyoto Encyclopedia of Genes and Genomes (KEGG) analysis indicated that KCNN4 was mainly enriched in primary immunodeficiency of KIRC, intestine immune network for IgA production of PAAD, and cytokine-cytokine receptor interaction shared by GBM, and LGG." (PMID 35720112, 2022).
renal cell carcinoma (1 paper, 2025). "Molecular docking findings indicate that the environmental endocrine-disrupting chemical BPA specifically interacts with key targets essential for the function of renal cell carcinoma cells, including CHRM3, GABBR1, CCR4, KCNN4, PRKCE, CYP2C9, HPGD, and FASN." (PMID 41301871, 2025).
Renal cyst (1 paper, 2025). A fluid filled sac in the kidney. "To assess Kcnn4 spatial expression in cystic kidneys, we examined early- and adult-onset Pkd1 mouse models of ADPKD by RNAScope." (PMID 41122971, 2025).
thalassemia (1 paper, 2018). An inherited blood disorder characterized by a decreased synthesis of one of the polypeptide chains that form hemoglobin. "Little research has been performed on KCNN4 (or also known as the Gardos channel in RBCs) in thalassemia." (PMID 29910743, 2018).
thyroid autoimmunity (1 paper, 2020). "Thus, we speculate that KCNN4 may be a valuable therapeutic target for PTC patients with coexistent thyroid autoimmunity." (PMID 32857728, 2020).
tumor (80 papers, 2012 to 2026). "The analysis of the immune cell heatmap reveals that KCNN4 is associated with an immunosuppressive tumor microenvironment in PAAD, as indicated by its correlation with various immune cell populations." (PMID 40952239, 2025). "Next, we performed correlation analysis of KCNN4 expression with tumor mutational burden (TMB) and microsatellite instability (MSI), and immune checkpoint genes (ICGs) to assess its potential as a predictor of immunotherapy efficacy." (PMID 35720112, 2022). "KCNN4 expression was correlated to tumor mutational burden and microsatellite instability levels in 14 types and 12 types of pan-cancers." (PMID 36313281, 2022). "Herein, we found significant correlations between KCNN4 and immune scores as well as stromal scores in four tumor types in the increased-risk group, whereas KCNN4 expression was associated with immune and stromal scores of the SKCM in the decreased-risk group." (PMID 35720112, 2022). "Correlation analysis of KCNN4 expression with tumor mutational burden (TMB), microsatellite instability (MSI), and immune checkpoint genes (ICGs) was then performed to explore its potential as a predictor of immunotherapy efficacy." (PMID 35720112, 2022). "Then we evaluated KCNN4 expression in PTC patients with different tumor grades, stages, subtypes and mutations in TCGA." (PMID 32857728, 2020). "Next, tumor malignancy association of KCNN4 was analyzed, and it showed significant differences." (PMID 39282155, 2023). "Targeted silencing of KCNN4 in PC-9 cells significantly reduced tumor aggressiveness, supporting its role as a therapeutic target." (PMID 41741906, 2026). "The analysis of KCNN4 expression at varying tumor stages reveals that the most substantial increase occurs in advanced‐stage tumors (Stage 4, p= 0.031), pointing to a prominent role of the channel in the late, metastatic phases." (PMID 40952239, 2025). "This suggests a potential role for KCNN4 in tumor progression; however, its specific involvement in metastatic dissemination requires further investigation." (PMID 40952239, 2025). "The analysis of KCNN4 expression at varying tumor stages reveals that the most substantial increase occurs in advanced‐stage tumor (Stage 4, p = 0.031), pointing to a prominent role of the channel in the late, metastatic phases." (PMID 40952239, 2025). "Meanwhile, KCNN4 also displayed an increasing trend of expression along with higher individual cancer stage and tumor grade." (PMID 39282155, 2023). "Multiple methods of bioinformatics analyses and fundamental experiments confirmed the obvious role of KCNN4 in promoting tumor progression in vitro." (PMID 39282155, 2023). "It is worth mentioning that KCNN4 expression exhibited the same trend with tumor stages and grades in ccRCC, indicating the potential direct relationship between KCNN4 and tumor malignancy." (PMID 39282155, 2023). "Various evidence indicates that KCNN4 is an important factor in radiation resistance and tumor proliferation." (PMID 37328854, 2023). "Overall, we made a comprehensive study on KCNN4 to prove its critical role in promoting the tumor progression and affecting the long-term prognosis of ccRCC patients." (PMID 39282155, 2023). "In mice inoculated with 2 × 105 cells, for example, the median tumor incidence times were 25 ± 3, 43 ± 1, and 32 ± 1 days for ov-KCNN4, sh-KCNN4, and lv-ctrl cells, respectively." (PMID 35805963, 2022). "In summary, our findings revealed that KCNN4 is an essential identity for remodeling components in the tumor microenvironment (TME), and a robust biomarker for predicting prognosis and immunotherapy response in pan-cancer patients." (PMID 35720112, 2022). "Firstly, in an orthotopic xenograft model of nude mouse, KCNN4-knockdown resulted in a reduction in tumor incidence (1/7 vs. 5/7) and loss of liver weight (1.24 ± 0.06 vs. 1.46 ± 0.09 g)." (PMID 35805963, 2022).
tumor (continued). "Altogether, these results suggested that KCNN4 promoted tumor formation by enhancing the ratio of stem cell population in HCC." (PMID 35805963, 2022). "Similar with nude mouse, ov-KCNN4 bearing mice displayed significantly larger tumor volume and higher tumor weight while sh-KCNN4 mice showed significantly smaller volume and lower weight, as compared with the lv-ctrl group in each level." (PMID 35805963, 2022). "As compared with the lv-ctrl group, median tumor incidence times were significantly longer in ov-KCNN4 but shorter in sh-KCNN4 mice." (PMID 35805963, 2022). "Conversely, KCNN4-overexpression promoted tumorigenicity and tumor growth, which was indicated by a significantly increased tumor incidence (7/7 vs. 5/7) and liver weight (1.88 ± 0.14 vs. 1.46 ± 0.09 g)." (PMID 35805963, 2022). "KCNN4 expression is higher in KIRC than in normal tissues, and its level is linked to the tumor stage and grade." (PMID 35983409, 2022). "In our validated cohort, KCNN4 expression also correlated significantly with the tumor size (p=0.028), LNM (p<0.030) and disease stage (p=0.009)." (PMID 32857728, 2020). "Next, the Tumor IMmune Estimation Resource (TIMER) database was used to perform a pan-cancer analysis of KCNN4 expression." (PMID 32857728, 2020). "Four consistent genes were differentially expressed in tumor tissues compared to normal tissues: two Ca2+-activated channels coding genes were induced (KCNN4, TRPM2) while KCNMA1 and TRPM6 were downregulated during the malignant transformation." (PMID 31010205, 2019). "Furthermore, GABRP interacts with KCNN4 and stimulates the Ca2+-NF-κB signaling pathway, leading to increase tumor cell growth, macrophage aggregation and tumor invasiveness." (PMID 40900801, 2025). "The reduced presence of NK cells implies that KCNN4 may suppress innate immune surveillance mechanisms, thereby facilitating tumor escape from immune destruction." (PMID 40952239, 2025). "Indeed, our analysis revealed a clear distinction between normal and tumor KCNN4 expression in PAAD, a result that was less evident in the study of Chen and colleagues due to the absence of samples from normal healthy tissues." (PMID 40952239, 2025). "According to previous studies, KCNN4 could influence tumor derivation, progression, and occurrence in many ways." (PMID 39282155, 2023). "Finally, in vitro experiments confirmed the remarkable tumor-promoting role of KCNN4 in ccRCC cells." (PMID 39282155, 2023). "KCNN4 significantly affected the immune status of tumor microenvironment and immunotherapy elements, through which it promoted tumor progression in ccRCC, and it could be a potential biomarker for prognosis and immunotherapy effects of ccRCC patients." (PMID 39282155, 2023). "KCNN4 influences tumor microenvironment by remodeling tumor-infiltrating immune cell profiles." (PMID 36313281, 2022). "Besides, KCNN4 was significantly tied in with survival indicators and clinical annotations, including tumor stages in multiple cancer types, which suggests its potential role as a prognostic biomarker for cancers." (PMID 35720112, 2022). "Notably, KCNN4 expression was upregulated in a variety of tumor tissues, including thyroid cancer, breast cancer, and hepatocellular carcinoma." (PMID 35720112, 2022). "Collectively, as a ceRNA hub gene, KCNN4 may function as a tumor promoter by recruiting Tregs and diminishing resting mast cells, and so inhibiting the anti-tumor immunity of the host." (PMID 35689211, 2022). "Furthermore, we analyzed the tumor-initiating ability in mice bearing xenografts with different levels of KCNN4." (PMID 35805963, 2022). "Briefly, KCNN4 may weaken anti-tumor immune response via raising Tregs and diminishing resting mast cells in ccRCC." (PMID 35689211, 2022).
tumor (continued). "Herein, we systematically dissected the prognostic value of KCNN4 in the pan-cancer dataset by combining multiple databases, including The Cancer Genome Atlas (TCGA), Tumor Immune Estimation Resource (TIMER), UALCAN, Clinical Proteomic Tumor Analysis Consortium (CPTAC), and cBioPortal databases." (PMID 35720112, 2022). "Combined targeting KCNN4 with its potential downstream signaling molecules, such as Glut1, may provide new possibilities for addressing tumor drug resistance." (PMID 35805963, 2022). "We found that tumor formation efficiency of 100% (9/9) occurred in mice injected with 2 × 103, 2 × 104, and 2 × 105 lv-ctrl CSCs, which occurred in all four cell numbers of ov-KCNN4 CSC-bearing mice but only in 2 × 104 or 2 × 105 sh-KCNN4 CSC-inoculated mice." (PMID 35805963, 2022). "In summary, the results demonstrated that KCNN4 may exert its influence on tumor biological behavior by affecting various components in the TME, especially immune components." (PMID 35720112, 2022). "The observed association between immune‐suppressive cell types (Tregs, neutrophils, and monocytes) and active oncogenic pathways suggests that KCNN4 may play a role in promoting tumor progression by facilitating immune evasion and diminishing antitumor immune responses." (PMID 40952239, 2025). "Results revealed close interaction between KCNN4 and several immune-related genes, suggesting that KCNN4 may interfere with the balance between anti- and pro-tumor effects in the TME by influencing the expression of immune-related genes, which in turn mediates tumor progression and metastasis." (PMID 35720112, 2022). "UALCAN database showed that high expression level of KCNN4 may be found in high tumor grade." (PMID 35689211, 2022). "Summarily, the role of KCNN4 in tumorigenesis has been supported by in vitro, and in vivo experiments, which is often recognized as an oncogene involving in the regulation of multiple cancer-related signaling pathways, thus mediating tumor progression, and development." (PMID 35720112, 2022). "In addition, this study hypothesized that KCNN4 could recruit Tregs and decrease resting mast cells, which could lead to tumor progression as well as poor prognosis." (PMID 35689211, 2022). "Our work suggests that KCNN4 may be an essential biomarker and tumor promoter in PTC." (PMID 32857728, 2020). "Given the critical role of KCNN4 in tumor immune microenvironment (TIM), TIMER database was employed to determine the effect of KCNN4 on immune cell infiltration level in ccRCC." (PMID 39282155, 2023). "More importantly, the expression levels of KCNN4 were not only vital to the tumor-initiating abilities but also to the stemness potentials with the LCSC frequency, which were 1/1, 1/1629, and 1/182 for ov-KCNN4, sh-KCNN4, and lv-ctrl CSCs, respectively." (PMID 35805963, 2022). "Unexpectedly, the immune score was positively correlated with KCNN4 expression in most of the tumor types in the two groups, and PAAD was the only pan-cancer type which was negatively correlated with KCNN4 expression." (PMID 35720112, 2022). "Moreover, the findings suggest that KCNN4 expression is upregulated in PAAD compared to normal tissue and remains high across different tumor stages, supporting its potential role in disease progression." (PMID 40952239, 2025). "They discovered that Kcnn4 and Scn2a1 channels exhibited similar expression levels in both non-tumor and tumor tissues, while the Kcna3 potassium channel were significantly overexpressed in tumor tissues." (PMID 39027429, 2024). "It is noteworthy that KCNN4 expression was significantly correlated with TMB levels in 14 tumor types, with MSI levels in 12 tumor types, and with expression levels of multiple ICGs in several tumor types." (PMID 35720112, 2022). "Only KCNN4 was significantly overexpressed in tumor tissues compared to nontumorous thyroid tissues." (PMID 32857728, 2020).